ETV1 (ETS variant transcription factor 1)
Description:
Transcriptional activator that binds to DNA sequences containing the consensus pentanucleotide 5'-CGGA[AT]-3'. Required for olfactory dopaminergic neuron differentiation; may directly activate expression of tyrosine hydroxylase (TH) (By similarity).
Synonyms: ER81
Tractability: PROTAC: UniProt records ubiquitination sites on it.
Gene: Protein-coding gene on chromosome 7 (13,891,229 to 13,991,425, reverse strand). Ensembl gene ENSG00000006468.
Subcellular location: Nucleus
Subcellular location (Human Protein Atlas): Nucleoplasm
Gene Ontology:
Molecular function: DNA-binding transcription activator activity, RNA polymerase II-specific; protein binding; RNA polymerase II cis-regulatory region sequence-specific DNA binding; sequence-specific double-stranded DNA binding; DNA-binding transcription factor activity; DNA-binding transcription factor activity, RNA polymerase II-specific; sequence-specific DNA binding
Biological process: positive regulation of transcription by RNA polymerase II; cell differentiation; peripheral nervous system neuron development; regulation of transcription by RNA polymerase II; transcription by RNA polymerase II; regulation of DNA-templated transcription
Cellular component: chromatin; nucleus
Genetic constraint (gnomAD): Loss-of-function variants: 19 observed, 42.37 expected, observed/expected ratio (o/e) 0.45, 90% interval 0.31 to 0.66. The upper end of that interval is the gene's LOEUF score, 0.66, which puts it in group 2 of 6, group 1 being the genes least tolerant of losing a copy. Missense variants: 480 observed, 511.66 expected, observed/expected ratio (o/e) 0.94, 90% interval 0.87 to 1.01. Synonymous variants: 198 observed, 177.86 expected, observed/expected ratio (o/e) 1.11, 90% interval 0.99 to 1.25.
Homologues: Orthologues: chimpanzee ETV1 (99% identical), mouse Etv1 (98% identical), macaque ETV1 (97% identical), pig ETV1 (96% identical), rat Etv1 (95% identical), guinea pig ETV1 (94% identical), dog ETV1 (94% identical), rabbit ETV1 (90% identical), tropical clawed frog etv1 (85% identical), zebrafish etv1 (76% identical). Paralogues in human: ETV5 (64% identical), ETV4 (56% identical), ETS1 (22% identical), ETS2 (22% identical), FLI1 (19% identical), ERG (18% identical), GABPA (18% identical), ELF2 (18% identical), ELF1 (16% identical), ETV6 (15% identical), ELF4 (14% identical), ETV2 (14% identical), and 16 more.
Diseases named in the same sentence as ETV1 in open-access papers:
ETV1 is named in the same sentence as 102 diseases in open-access papers, as found by Europe PMC text mining. Sharing a sentence is not in itself a finding about the gene and the disease. The quoted sentences say what the papers report.
prostate carcinoma (138 papers, 2007 to 2025). A carcinoma that arises from epithelial cells of the prostate gland. "For instance, ETV1 is associated with prostate cancer; RFX3-AS1, MRPS30, MRPS30-DT, and MIR3201 are associated with breast cancer; MIR548H4, AATF, and APCDD1L-DT are associated with lung cancer." (PMID 40440618, 2025). "In particular, these genes have been found to be associated with various types of cancer, such as prostate cancer, where ETV1 and ETV4 were often found overexpressed." (PMID 41304759, 2025). "underlined the pivotal roles of ERG (ETS‐related gene) and ETV1 (ETS translocation variant 1) in the landscape of prostate cancer." (PMID 39374163, 2025). "Gene microarray studies have also revealed Ets Variant Gene 1 (ETV1) as an AR-regulated gene that mediates prostate cancer cell invasion." (PMID 39459070, 2024). "Negative regulation of prostate cancer growth and invasion by stromal AR have also been reported, and Ets Variant Gene 1 (ETV1) was identified as a novel androgen-regulated gene." (PMID 39459070, 2024). "High ETV1 levels are correlated with shorter prostate-specific antigen (PSA) recurrence in prostate cancer, while nuclear overexpression of ETV1 is associated with longer overall survival in esophageal adenocarcinoma." (PMID 36109787, 2022). "The ETS transcription factor ETV1 is frequently overexpressed in aggressive prostate cancer, which is one underlying cause of this disease." (PMID 31160676, 2019). "Lastly, ETV4 and ETV5 are highly homologous to ETV1 and also implicated in prostate cancer development." (PMID 31160676, 2019). "PEA3 transcription factors Etv1, Etv4, and Etv5 overexpression is associated with the development and metastasis of prostate cancer, colorectal cancer, and ovarian cancer." (PMID 30610188, 2019). "We attempted to prove that ETV1 overexpression cooperates with SMAD4 loss in the development of prostate cancer by emulating such a situation with our ETV1;Pb-Cre4;Smad4f/f compound mice." (PMID 31160676, 2019). "ACSL3 is an androgen receptor (AR)-stimulated gene and was recently identified in formalin-fixed prostate cancer tissue as a new 5′ translocation partner of ETS variant 1 (ETV1), an important gene in driving prostate cancer progression." (PMID 29156692, 2017). "Etv1 directly interacts with the androgen receptor and drives the androgen receptor transcriptional response associated with aggressive prostate cancer." (PMID 25866208, 2015). "Studies in murine models suggest that ETV1 expression is an underlying cause of prostate cancer initiation." (PMID 25479232, 2014). "ETV1 (ETS translocation variant 1) however, is an androgen responsive transcription factor which has an established role in regulation of prostate growth and prostate cancer progression." (PMID 24077328, 2013). "Somatic mutations in prostate cancer gives rise to chromosomal rearrangements that juxtapose the coding sequence of an ETS family transcription factor gene (most commonly ERG or ETV1) next to the androgen –related TMPRSS2 promoter." (PMID 24063260, 2013). "Here, we show, using cell models of advanced prostate cancer, that ETS translocation variant 1 (ETV1) and transcriptional regulator ERG (ERG) transcription factors (members of the ETS family) promote tumour properties, and that activation of MET signalling enhances these effects." (PMID 39374163, 2025). "Notably, CIC and ERF have been shown to co-regulate the expression of ETV1 in prostate cancer, where their combined loss and the subsequent increase in ETV1 expression contribute to disease progression." (PMID 37345142, 2023). "Recently, recurrent fusions between the transmembrane protease serine 2 (TMPRSS2) gene and members of the ETS family of transcription factors (mainly the v-ets erythroblastosis virus E26 oncogene homolog (avian), ERG, and the ets variant 1, ETV1) were reported in prostate cancer." (PMID 20964841, 2010).
prostate carcinoma (continued). "In this study, by using cellular models of advanced prostate cancer, we undertake an investigation of ETV1/ERG transcription factors and MET signalling interplay in tumour progression mechanic." (PMID 39374163, 2025). "The MET receptor activation pathway is intrinsically linked to the activity of the transcription factors ETV1 and ERG (ETS family) to promote tumorigenesis in prostate cancer cells." (PMID 39374163, 2025). "ETV1 can stabilize β‐catenin, which leads to increased accumulation of β‐catenin in prostate cancer cells and promotes malignant transformation of tumors." (PMID 39668941, 2025). "Studies have found that ETV1 has the highest expression in prostate cancer and has the most specific expression in gastrointestinal stromal tumor; moreover, its expression in gastric cancer is also significantly increased." (PMID 39668941, 2025). "ERG rearrangements are found in 40–50% of the prostate carcinomas, ETV1 rearrangements/overexpression in 8–10%, and rearrangements involving ETV4, ETV5, or FLI1 in 2–5% of the cases, being mutually exclusive." (PMID 40808640, 2025). "Previous documents report that up-regulated ETV1 enhances tumor aggressiveness in pancreatic cancer, prostate cancer and gastrointestinal stromal tumor." (PMID 38730434, 2024). "ETV1 plays a key role in mediating androgen metabolism and is frequently over expressed in advanced prostate cancer, where chromosomal rearrangements (TMPRSS2 fusion) are common." (PMID 38667288, 2024). "Disruption of ETV1 expression in both cell types significantly compromised their invasion capacity, suggesting an important role for ETV1 in prostate cancer invasion." (PMID 39459070, 2024). "It is suggested that Etv1 is involved in different processes in multiple malignant tissues, such as carcinogenesis of prostate cancer, cell survival of gastrointestinal stromal tumor, and metastasis of pancreatic cancer." (PMID 37045597, 2023). "In vitro invasion assays showed that PARP-1 inhibition attenuates Erg- and Etv1-dependent invasion in prostatic cancer cell lines." (PMID 37686260, 2023). "Downregulation of JMJD2A inhibited prostate cancer cell growth, whereas its overexpression in a transgenic mouse model led to the formation of prostatic intraepithelial neoplasia and cooperated with ETV1 to induce adenocarcinoma." (PMID 37870957, 2023). "ERF and CIC were also recently shown to coordinate to regulate ETV1 expression in prostate cancer cells, further supporting the notion that the two proteins function similarly and, at least in one context, cooperatively." (PMID 37345142, 2023). "In prostate cancer, androgen receptor activation mediates ETV1 expression, activating Twist1, leading to EMT and tumor metastasis." (PMID 37197420, 2023). "One potential explanation for the minimal phenotype is the low dosage level of achievable ETS (e.g., ERG or ETV1) proteins in previous ETS-driven murine prostate cancer models." (PMID 37018402, 2023). "For example, miR-129-5p can regulate the expression of COL1A1 so as to promote the progression of gastric cancer, regulate YWHAB to affect the progression of lung cancer, and target ETV1 to inhibit prostate cancer proliferation." (PMID 36193492, 2022). "The 5′ LTR, which is the known promoter of HML-2 element and regulates its expression, was discovered to be fused to the oncogene ETV1 in prostate cancer cell lines, promoting ETV1 expression and cancer cell invasion." (PMID 36146825, 2022). "For example, ETV1 is frequently dysregulated in prostate cancer and reported to be overexpressed in the most aggressive prostate tumors." (PMID 36109787, 2022). "Recurrent fusions at the TMPRSS2 5′ UTR (untranslated region) to ETV1 (ETS variant transcription factor 1) or ERG (ETS-related gene) lead to outlier expression and drive progression of prostate cancer." (PMID 36364238, 2022). "ETV1 induces cell migration and invasion of prostate cancer via stabilizing β-catenin and directly binding to MMP1/7." (PMID 36109787, 2022).
prostate carcinoma (continued). "ERG and TMPRSS2 fusion is found in about 50% of prostate cancers, and ETV1 and TMPRSS2 fusion is found in 5% of prostate cancers." (PMID 36289913, 2022). "As a member of ETS/PEA3 family, ETV1 has been well documented to represent oncogenic drivers across several tumors including prostate cancer, Ewing sarcoma and GIST." (PMID 36109787, 2022). "The best known fusion genes associated with prostate cancer involve ETS transcription factor family members and the androgen-regulated promotor TMPRSS2 (TMPRSS2:ERG, TMPRSS2:ETV1, and TMPRSS2:ETV4)." (PMID 35625354, 2022). "PXN expression was relatively high in ERG1- and FLI1-fusion-positive prostate cancers and SPOP-mutant prostate cancer, but it was relatively low in ETV1- and ETV4-fusion-positive prostate cancers." (PMID 36289913, 2022). "Tomlins used FISH to evaluate the TMPRSS2:ETV1 fusion gene in paraffin sections of prostate cancer and found that, fusion signals were observed in an average of 31% of the 100 cancer cells in the positive case (Supporting Online Material page 3)." (PMID 34676167, 2021). "Consistent with an involvement of ETS transcription factors in control of HSD17B7 expression, this gene is part of transcriptional network described in ETV1‐overexpressing prostate cancer cells." (PMID 34185380, 2021). "It will be interesting to determine in future work if the AR indirect up-regulation of Twist1 via ETV1 is involved in these other steps of prostate cancer metastasis." (PMID 32296610, 2020). "Based on genomic profiles, prostate cancer can be divided into seven molecular subtypes which bear distinct oncogenic drivers including fusions with ETS family members (ERG, ETV1, ETV4, and FLI1) and mutations in SPOP, FOXA1, and IDH1." (PMID 33273988, 2020). "The role of ERG and ETV1 in prostate cancer has been thoroughly studied, whereas the mechanisms whereby overexpression of ETV4 mediates oncogenesis in the prostate have not been investigated in depth." (PMID 32791988, 2020). "IGF2 and ETV1 are well-known oncogenes, previously observed with focal amplification in colorectal cancer and as gene-gene fusion in prostate cancer, respectively." (PMID 32631391, 2020). "An earlier study of a cohort of 333 primary prostate carcinomas showed that 74% of these tumors fell into one of seven subtypes of a molecular taxonomy defined by specific gene fusions (ERG, ETV1/4 and FLI1) or mutations (SPOP, FOXA1 and IDH1)." (PMID 33058520, 2020). "A study of a cohort of 333 primary prostate carcinomas showed that 74% of these tumors fell into one of seven subtypes of a molecular taxonomy defined by specific gene fusions (ERG,ETV1/4 and FLI1) or mutations (SPOP,FOXA1 and IDH1)." (PMID 33058520, 2020). "Collectively, these data strongly argue that ETV1 regulates basal Twist1 expression and, more importantly, mediates the androgen-dependent expression of Twist1 in prostate cancer cells." (PMID 32296610, 2020). "All this suggests that ETV1 is required for efficient growth and aggressiveness/metastasis during prostate cancer progression." (PMID 31160676, 2019). "Accumulating evidence indicates a role of transcription factor ETV1 in prostate cancer tumorigenesis and progression." (PMID 30041429, 2018). "This implicates the long non-coding gene AL121790.1 as a facilitator in two distinct prostate cancer driving mechanisms (FOXA1 mutations and ETV1 fusions)." (PMID 30272002, 2018). "Since the anti-tumor efficacy of YK-4-279 in Ewing’s sarcoma was demonstrated in 2009, ERG/ETV1-mediated prostate cancer and EWS-FLI1-induced leukemia have been verified as additional target diseases." (PMID 29212266, 2017). "Several studies have demonstrated the anti-tumor efficacy of YK-4-279 in Ewing’s sarcoma, ERG- and ETV1-mediated prostate cancer and EWS-FLI1-induced leukemia." (PMID 29212266, 2017).
prostate carcinoma (continued). "Given the expression of the ets genes ERG and ETV1 in prostate cancers, YK-4-279 was also tested in prostate cancer cell lines, demonstrating its ability to reduce cell motility and tumor invasion." (PMID 26885691, 2016). "The ETS family member ETV1 (ETS variant 1) is a transcription factor frequently involved in oncogenic translocations, particularly in prostate cancer." (PMID 27980689, 2016). "Translocations of the ETS transcription factors, including ETV1, occur in half of all prostate cancers resulting in aberrant ETS transcription factor expression which are believed to be an early, potentially initiating event, for prostate cancer." (PMID 25658610, 2015). "YK-4-279 targets EWS-FLI1, inhibits growth in Ewing sarcoma, and also inhibits Erg/Etv1-driven prostate cancer invasion." (PMID 25866208, 2015). "We recently have shown that GRPR is an ERG and ETV1 target gene in prostate cancer, using a genome-wide scale and exon-level expression microarray platform." (PMID 26097883, 2015). "Studies suggest an oncogenic role for ETV1 in different cancers, due to its tumor-promoting functional features, for example proliferation of breast cancer, proliferation and invasion of prostate cancer." (PMID 26158900, 2015). "Expression of GRPR, both at mRNA and protein levels, was detected in ERG and ETV1 rearrangement-positive prostate cancer cell lines VCaP and LNCaP, respectively." (PMID 26097883, 2015). "MMP7 has been shown to be overexpressed in prostate cancer tissue when compared to normal tissue and was recently demonstrated to be regulated by the ETV1 transcription factor." (PMID 25658610, 2015). "Our group has shown that YK-4-279 binds to ERG and ETV1 and inhibits their activity in prostate cancer cell lines and show anti-metastatic activity in vivo." (PMID 26462019, 2015). "Consistent with these, in a tissue reconstitution model, lentiviral overexpression of ERG (or ETV1) in prostate cells collaborates with activation of the PI3K pathway or the androgen receptor (AR) pathway to induce distinct prostate carcinomas." (PMID 25780911, 2015). "The two ETS factors ERG and ETV1 reprogram the androgen receptor cistrome with consequences for androgen ablation therapy in prostate cancer." (PMID 26462019, 2015). "Additional functional studies to examine the potential role of allele-specific transcriptional regulation of MMP7 by rs11568818 and ETV1 for prostate cancer should be conducted." (PMID 25658610, 2015). "YK-4-279 inhibited ERG and ETV1 derived malignant phenotypes in prostate cancer cells both in vitro and in vivo." (PMID 26462019, 2015). "The most prevalent gene fusion is the TMPRSS2-ERG, present in nearly half of all human prostate cancers, followed by rearrangements involving the ETV1, ETV4, ETV5 and FLI1 genes, often with promoter fusion partners other than TMPRSS2." (PMID 25595908, 2015). "ETV1 is a transcription factor, which has been shown to enhance the migration of prostate cancer cells." (PMID 26158900, 2015). "We recently have shown that gastrin-releasing peptide receptor (GRPR) is an ERG and ETV1 target gene in prostate cancer, using a genome-wide scale and exonlevel expression microarray platform." (PMID 26316886, 2015). "We also demonstrate that the effects of YK-4-279 on ETV1 and prostate cancer cell lines are enantiospecific and (S)-YK-4-279 enantiomer is the active component confirming similar findings in other tumor models." (PMID 25479232, 2014). "As EWS–FLI1 includes the FLI1 Ets portion and some upstream regions, both RHA and YK-4-279 potentially directly bind the Ets domain, particularly as YK-4-279 also inhibits ERG and ETV1-mediated invasion in prostate cancer." (PMID 24450640, 2014). "Our results demonstrate that YK-4-279 is a potent inhibitor of ETV1 and inhibits both the primary tumor growth and metastasis of fusion positive prostate cancer xenografts." (PMID 25479232, 2014).